RN7SL279P (RNA, 7SL, cytoplasmic 279, pseudogene)
Gene: Miscellaneous RNA gene on chromosome 16 (70,276,069 to 70,276,352, forward strand). Ensembl gene ENSG00000265648.
Homologues: Orthologues: chimpanzee Metazoa_SRP (96% identical). Paralogues in human: RN7SL32P (79% identical), Metazoa_SRP (78% identical), Metazoa_SRP (76% identical), RN7SL850P (76% identical), RN7SL377P (74% identical), Metazoa_SRP (74% identical), Metazoa_SRP (73% identical), RN7SL155P (72% identical), RN7SL48P (72% identical), Metazoa_SRP (71% identical), RN7SL716P (71% identical), RN7SL356P (70% identical), and 700 more.